HOTAIR (HOX transcript antisense RNA)
Diseases named in the same sentence as HOTAIR in open-access papers (continued):
Sharing a sentence is not in itself a finding about the gene and the disease.
glioblastoma (continued). "Through ChIP-PCR analysis, it was shown that after knockdown of the expression of HOTAIR in glioblastoma, the binding of histone H3K27me3 in the promoter region of the PPARα gene was significantly reduced." (PMID 34082742, 2021). "Treatment of glioblastoma cells with the BET bromodomain inhibitor I-BET151 reduced levels of HOTAIR and restored the expression of several other glioblastoma downregulated lncRNAs." (PMID 34576322, 2021). "HOTAIR has critical roles in numerous cancers, it is overexpressed in glioblastoma, and functions in cell proliferation." (PMID 32650527, 2020). "HOTAIR depletion acts as an anti-cancer agent in glioblastoma, regulating the FGF1-dependent pathway through miR-326." (PMID 32283739, 2020). "HOTAIR and GAS5 levels were associated with 2-year overall survival and disease-free survival in patients with glioblastoma." (PMID 33053907, 2020). "Primary patient-derived glioblastoma cells expressed higher levels of HOTAIR and EZH2 compared with N33 cells." (PMID 31367244, 2019). "It was found that HOTAIR overexpression was significantly associated with worse OS in adrenocortical carcinoma (ACC), mesothelioma (MESO), and glioblastoma multiforme (GBM)." (PMID 31195674, 2019). "HOTAIR promotes glioblastoma cell cycle progression in an EZH2 dependent manner, while its reduction induced colony formation suppression, cell cycle G0/G1 arrest, and orthotopic tumor growth inhibition." (PMID 26252651, 2015). "Thus, HOTAIR robustly reduced the expression of SNORD76, and involvement of HOTAIR/SNORD76 signaling in glioblastoma pathogeneses was confirmed both in nude mice with ectopically transplanted U87 cells, and in brain tumor specimens from human subjects." (PMID 38366205, 2024). "Finally, HOTAIR is regulated by the glioblastoma proliferative pathway, specifically by bromodomain and extra-terminal domain proteins, such as bromodomain-containing 4 (BRD4), which binds to and increases HOTAIR levels in this pathway." (PMID 33980320, 2021). "Resistant glioblastoma cells showed decreased expression levels of HOTAIR." (PMID 33806782, 2021). "HOTAIR promotes glioblastoma cell cycle progression in an EZH2-dependent manner." (PMID 34405017, 2021). "The diagnostic power of lncRNAs SAMMSON, HOTAIR, MALAT1, H19, and LINR-ROR has been assessed in serum or tissue samples of pateints with glioblastoma revealing the best results for the first two mentioned lncRNAs based on the high values of the area under the reciver operating characteristic curves." (PMID 33634032, 2020). "Additionally, HOTAIR knockdown inhibited glioblastoma formation in vivo, indicating that this lncRNA was required for tumor development." (PMID 32283739, 2020). "HOX Transcript Antisense RNA (HOTAIR) was detected as a negative prognostic factor in several cancers, including glioblastoma, and to be significantly associated with overall survival." (PMID 33053907, 2020). "The levels in serum samples from glioblastoma patients was significantly higher when compared with those of control healthy subjects, demonstrating that HOTAIR may be used as a prognostic biomarker for glioblastoma." (PMID 32283739, 2020). "Similarly, in glioblastoma, the lncRNA HOTAIR is upregulated in temozolomide-resistant cells." (PMID 40781643, 2025). "HOTAIR could promote glioblastoma cell cycle progression; FOXM1-AS could enhance self-renewal and tumorigenesis of glioblastoma stem-like cells; H19 could promote glioblastoma cell invasion, angiogenesis, and tube formation; MALAT1 could decrease the sensitivity of glioblastoma cells to TMZ." (PMID 34759954, 2021). "Furthermore, it has been shown that BRD4 binds to the HOTAIR promoter and that treatment of glioblastoma cells with I-BET151 (an inhibitor against BRD4 and others in the bromodomain and extraterminal domain (BET) protein family) reduced levels of HOTAIR transcripts." (PMID 34207158, 2021).
glioblastoma (continued). "Targeting CDK9 may thus provide a mechanism to reduce HOTAIR expression in glioblastomas as well." (PMID 34207158, 2021). "In contrast, a study reported diminished expression of HOTAIR lncRNA in U118, MG-U87, and MG-LN18 glioblastoma cells; however, it used human parental brain cancer stem cell line as controls." (PMID 38366205, 2024). "Upon hypoxia, hypoxia-inducible factors (HIFs) modulate many ncRNAs, including MALAT1, the lncRNA HOTAIR in non-small cell lung cancer (NSCLC), and the lncRNA H19 in glioblastoma." (PMID 36012617, 2022). "In glioblastoma (GBM), the depletion of HOTAIR restrained HK2 expression by regulating miR-125, which facilitated cell apoptosis and elevated temozolomide (TMZ) sensitivity." (PMID 36100611, 2022). "STEAP3-AS1, together with HOTAIR and SOX21-AS1, as the exo-lncRNA signature, was proven to be an independent prognostic factor in glioblastoma (GBM)." (PMID 34655361, 2021). "A CGGA database analysis based on 301 patients revealed high HOTAIR expression in WHO III and IV grade glioblastoma samples, especially in classical and mesenchymal glioblastomas." (PMID 34887871, 2021). "HOTAIR and the HOTAIR/miR-326/FGF1 axis are a promising therapeutic strategy for glioblastoma therapy." (PMID 32283739, 2020). "Thus, HOTAIR could be a potential therapeutic target in glioblastoma." (PMID 31191605, 2019). "Moreover, in glioblastoma (GBM), HOTAIR competitively binds to miR-526b-3p, limiting its ability to bind EVA1." (PMID 39940704, 2025). "In primary patient-derived glioblastoma cells, AQB was found to robustly repress HOTAIR signaling, resulting in beneficial induction of tumor suppressor gene, APC regulator of WNT signaling pathway 2 (APC2), and concomitant suppression of Wnt/β-catenin signaling cascade." (PMID 38366205, 2024). "Further, serum levels of GAS5 lncRNA were found to be linked with diminished tumor recurrence and progression, indicating the possible utilities of circulating HOTAIR and GAS5 in serving as potential reciprocal predictors of disease prognosis and survival in glioblastomas." (PMID 38366205, 2024). "Moreover, HOTAIR suppressed the β-catenin pathway, leading to cell cycle arrest and repression of invasion, putatively by downregulating Nemo-like kinase (NLK) in glioblastoma." (PMID 34322395, 2021). "Transcriptome analysis was carried out to evaluate the expression of the HOX genes and HOTAIR in several pediatric tumors such as teratoid rhabdoid tumors (ATRT), ependymomas, medulloblastomas, glioblastoma multiforme and juvenile pilocytic astrocytomas (JPAs)." (PMID 34576322, 2021). "Determining treatment response: Expression of HOTAIR was higher in non-TMZ responder glioblastoma patients compared to responders." (PMID 34322395, 2021). "Because of this inverse correlation between HOTAIR and SNORD47 expression, we postulated that SNORD47 may be characterized as a suppressive molecule in glioblastoma." (PMID 28410200, 2017). "HOTAIR is a negative prognostic factor and is overexpressed in multiple human cancers including glioblastoma multiform (GBM)." (PMID 25823657, 2015). "Experimental analyses confirmed AQB's robust inhibitory actions on HOTAIR, and the consequent upregulation of tumour suppressor gene, antigen-presenting cell (APC) regulator of WNT signalling pathway 2 and repression of Wnt/β-catenin cascade in primary patient-derived glioblastoma cells, N5 and N33." (PMID 38682637, 2024).
lymph node metastasis (48 papers, 2013 to 2025). "Some studies found that HOTAIR positivity was associated with lymph node metastasis and higher TNM stage." (PMID 35347094, 2022). "Remarkably, higher HOTAIR serum levels were also associated with advanced T-stage, lymph node metastasis and LVSI, thereby impairing survival." (PMID 34830902, 2021). "The increased expression of HOTAIR is associated with lymph node metastasis; therefore, the HOTAIR expression level is associated with lymph node metastasis." (PMID 31341758, 2019). "In conclusion, findings from this meta-analysis indicate that higher expression of lncRNA HOTAIR is associated with poor prognosis, advanced tumor stage and higher rate of lymph-node metastasis." (PMID 29069846, 2017). "We found that HOTAIR expression was associated with vascular invasion, nuclear grade, lymph-node metastasis, and distant metastasis." (PMID 28931862, 2017). "For clinicopathological features, HOTAIR expression was positively associated with tumor size (odds ratio [OR]=2.19, 95% confidence interval [CI] 1.42-3.38, P=0.000) and lymph node metastasis (OR=6.04, 95% CI 3.51-10.42, P=0.000)." (PMID 29108287, 2017). "A total of 2070 patients in 23 studies were analyzed to determine an association between HOTAIR expression and lymph node metastasis." (PMID 28591050, 2017). "In cervical cancer samples, overexpression of HOTAIR was associated with lymph node metastasis and shorter survival time." (PMID 27686732, 2016). "Furthermore, we observed a significant association of the HOTAIR rs920778 variant allele T with lymph node metastasis, tumor recurrence, and progression-free survival." (PMID 38339237, 2024). "Therefore, HOTAIR overexpression is associated with the presence of lymph node metastases and inferior overall survival." (PMID 34830902, 2021). "The result showed that HOTAIR expression was significantly associated with lymph node metastasis (OR = 3.11, 95% CI = 2.15–4.49, P < .001), suggesting that patients with increased HOTAIR expression were at high risk of developing lymph node metastases." (PMID 28591050, 2017). "Moreover, they observed that high HOTAIR expression levels were associated with an advanced stage, lymph node metastasis, and poor prognosis, whereas patients with a lower expression of HOTAIR experienced a longer overall survival." (PMID 25593996, 2014). "Meta-analysis revealed that high expression of HOTAIR was associated with poor overall survival (HR, 1.90; 95% CI: [1.42, 2.53]; p < 0,0001), advanced tumor stage (OR, 3.44; 95% CI: [1.84, 6.43]; p < 0,001) and lymph-node metastasis (OR, 3.31; 95% CI: [1.24, 8.79]; p = 0,02)." (PMID 29069846, 2017). "Another study confirmed that the upregulation of HOTAIR in NSCLC was associated with advanced pathological stage and lymph node metastasis, and patients with high levels of HOTAIR expression had a relatively poorer prognosis." (PMID 37526759, 2023). "HOTAIR upregulation was shown to be strongly related to lymph node metastasis in patients with TNBCs, despite the fact of how it controls lymph node metastasis, as well as BC lung metastasis, are not well understood." (PMID 34830241, 2021). "We also found that the expression of HOTAIR mRNA significantly correlated with distant metastasis (P = 0.01), lymph node metastasis (P = 0.0001), MMR index (P = 0.034) and depth of invasion (P = 0.011)." (PMID 32489462, 2020). "The cancer sufferers with lymph node metastasis and vessel invasion also more frequently possessed higher‐level HOTAIR and miR‐17‐5p expressions than ones whose lymph node metastasis and vessel invasion were unobserved (P < 0.05)." (PMID 30338929, 2019). "HOTAIR expression in LSCC tissues is 16-fold higher than in normal tissues, and increase in HOTAIR expression is statistically correlated with advanced tumor grade, lymph node metastasis (LNM), poor differentiation and advanced clinical stages." (PMID 27802187, 2017).
lymph node metastasis (continued). "For example, HOTAIR up-regulation was correlated with non-small-cell lung cancer advanced pathological stage and lymph node metastasis, and patients with high levels of HOTAIR expression had a relatively poor prognosis." (PMID 29046366, 2017). "By integrating 44 studies with 4116 patients, our comprehensive meta-analysis revealed that a higher expression of HOTAIR was correlated with an advanced clinical stage, lymph node metastasis, poor differentiation, and a worse prognosis." (PMID 28591050, 2017). "HOTAIR expression in tumors was significantly correlated with nuclear grade, lymph-node metastasis, and lung metastasis." (PMID 28931862, 2017). "Of the clinicopathological variables, age, gender, clinical tumor stage, lymph node metastasis, degree of differentiation, and tumor size were selected, and their relationships with HOTAIR expression were analyzed." (PMID 28591050, 2017). "Of 77 cases of non-small cell lung cancer (NSCLC), 17 (22 %) exhibited high expression of HOTAIR, and these patients were more frequently in an advanced stage with lymph node metastasis or lymph-vascular invasion and had a shorter disease-free interval." (PMID 27686732, 2016). "Enhanced expression of HOTAIR in epithelial ovarian cancer (EOC) tissues was associated with clinical stage, pathological classification, lymph node metastasis, reduced OS, and shorter disease-free survival (DFS)." (PMID 27686732, 2016). "They identified that patients with high expression of HOTAIR had a high incidence of lymph node metastasis." (PMID 27143813, 2016). "Examination of the correlation between HOTAIR expression and clinical pathological features showed that HOTAIR upregulation was correlated with lymph node metastasis and vasculature invasion." (PMID 26136075, 2015). "On the other hand, HOTAIR levels were increased in tumor samples from patients with lymph node metastasis." (PMID 25334066, 2014). "It has been demonstrated that a significant correlation between HOTAIR gene expression and lymph node metastasis exists, suggesting that measuring HOTAIR lncRNA is a potential biomarker for predicting lymph node metastasis." (PMID 23443164, 2013). "Our results showing that carriers of the HOTAIR rs920778 TT genotype have a higher incidence of lymph node metastasis, higher rates of tumor recurrence, and lower progression-free survival are consistent with previous studies associating this polymorphism with the progression of multiple cancers." (PMID 38339237, 2024). "HOTAIR expression has been shown to be associated with lymph node metastases but not with tumor size or grading." (PMID 36376369, 2022). "Additionally, its expression in tissues of patients with TNM stages III or IV, nerve invasion, lymph node metastasis and poor survival rate is increased, suggesting that HOTAIR is a potential marker for prognostic assessment of patients with SACC." (PMID 34576322, 2021). "In support of this hypothesis, 2 meta-analysis studies have analyzed the large amount of data produced in recent years, showing that high HOTAIR expression in tumor tissue is strongly correlated with lymph node metastasis." (PMID 30541551, 2018). "Moreover, HOTAIR expression strongly related to lymph node metastasis in patients with preoperative treatment (OR = 7.65, 95% CI = 2.12–27.57, P = .002) and without preoperative treatment (OR = 2.99, 95% CI = 2.01–4.46, P < .001)." (PMID 28591050, 2017). "For lymph node metastasis, the high level of HOTAIR expression might be more meaningful in predicting lymph node metastasis in estrogen-dependent carcinomas, digestive system cancers, and OSCCs." (PMID 28591050, 2017). "High HOTAIR expression correlated with lymph node metastasis, and reduced overall survival." (PMID 25405331, 2015). "In contrast, HOTAIR expression was correlated with lymph node metastasis (P=0.0437)." (PMID 25405331, 2015). "Among the tested lncRNAs, HOTAIR was the most highly expressed in lymph node metastasis." (PMID 23862139, 2013).
lymph node metastasis (continued). "Similarly, high expression of HOTAIR is correlated with tumor depth, lymph node metastasis, organ metastasis, histological differentiation, vascular invasion, and advanced tumor stage, and patients with HOTAIR upregulation show a poor clinical prognosis such as lower metastasis-free survival and OS." (PMID 26307974, 2015). "Higher expression of HOTAIR was related to TNM stage, tumor differentiation, and lymph node metastasis." (PMID 33954114, 2021). "HOTAIR was upregulated in primary LSCC, compared with adjacent noncancerous tissues and its overexpression was correlated with poor differentiation, lymph node metastasis and advanced clinical stages." (PMID 34576322, 2021). "HOTAIR expression was significantly correlated with TNM stage, lymph node metastasis, and shorter patient survival after surgery." (PMID 28938586, 2017). "In recent study, HOTAIR expression was elevated in EOC tissues, and its level of expression is highly positively correlated with FIGO stage, histological grade, lymph node metastasis, reduced overall survival, and disease-free survival." (PMID 26448935, 2015). "HOTAIR upregulation was correlated with NSCLC advanced pathological stage and lymph-node metastasis." (PMID 24103700, 2013). "HOTAIR expression is significantly higher in the serum of PTC patients with lymph node metastases than in metastasis-negative patients." (PMID 38339237, 2024). "In addition, patients with lymph node metastasis exhibited higher expression of HOTAIR than those without metastasis, with a pooled OR of 6.04 (95%CI 3.51-10.42, P = 0.000)." (PMID 29108287, 2017). "In addition, patients with lymph node metastasis had higher serum exosomal HOTAIR expressions than those with no metastases, suggesting that circulating HOTAIR could be a valuable biomarker to screen and predict progression for LSCC patient." (PMID 34576322, 2021). "Indeed, HOTAIR, found in exosomes isolated from serum of laryngeal squamous cell carcinoma patients, is elevated in samples from patients with lymph node metastasis relative to patients without lymph node metastasis, increasing also with progressive disease stage." (PMID 26516918, 2015). "Well-documented lncRNAs, such as MALAT1 and HOTAIR, are present in the saliva of OSCC patients; notably, patients with lymph node metastasis exhibit higher HOTAIR expression than those with non-metastatic patients." (PMID 39769275, 2024).